GPC3 (glypican 3)
Diseases named in the same sentence as GPC3 in open-access papers (continued):
Sharing a sentence is not in itself a finding about the gene and the disease.
hepatoblastoma (39 papers, 2010 to 2025). Hepatoblastoma (HB) is a malignant hepatic tumor and is the most common pediatric liver cancer. "Loss of function mutations in GPC3 lead to Simpson-Golabi-Behmel Syndrome, an X-linked overgrowth condition with a predisposition to GPC3-expressing cancers including hepatoblastoma and Wilms tumor." (PMID 30873384, 2019). "Multiple germline variants in GATA2 predispose individuals to familial myelodysplastic/acute leukemia syndrome, while germline GPC3 variants are observed in Simpson-Golabi-Behmel syndrome, an overgrowth syndrome that increases the risk of developing Wilms tumor, hepatoblastoma, and neuroblastoma." (PMID 37461096, 2023). "Similarly, HOGCN predicts association for GPC3 and Hepatoblastoma." (PMID 33587705, 2022). "These tumors resemble hepatoblastoma based on their early onset, their characteristic histology and the expression of specific markers such as GPC3 and EPCAM, but most importantly high MYC expression." (PMID 39529166, 2024). "Glypican 3, a known marker expressed in hepatoblastoma tumors, was predominantly expressed in hepatoblastoma tumor cells but not in normal hepatocytes." (PMID 39684755, 2024). "In hepatoblastoma tumors, Glypican 3 (GPC3) is a frequently overexpressed cell surface heparan sulfate proteoglycan." (PMID 39684755, 2024). "In this paper, the pathological staining findings of Cytokeratin 17, AFP, Hepatocyte and Glypican 3 in the tumor tissue clearly indicated a fetal epithelial subtype of hepatoblastoma." (PMID 38819760, 2024). "Glypican-3 (GPC3), a canonical Wnt-targeted gene specifically expressed in hepatoblastoma, offers a promising avenue for targeted therapy." (PMID 38390281, 2024). "Then we specifically investigated the individual genes that indicate hepatocyte differentiation (Cyp2e1), hepatoblastoma markers (Igf2, Afp, Glul, Krt19) and embryonal hepatoblastoma stem cell markers (Dlk1, Epcam and Gpc3)." (PMID 37414763, 2023). "Specifically, we choose gene-disease pairs (a) ABO and Pancreatic carcinoma (26 pieces of evidence) and (b) GPC3 and Hepatoblastoma ((17 pieces of evidence)." (PMID 33587705, 2022). "GPC3 was the second most highly transcriptionally overexpressed gene in a study of 48 hepatoblastoma tumors compared to normal liver." (PMID 30873384, 2019). "GPC3 is expressed in some pediatric cancers, including hepatoblastoma, nephroblastoma (Wilms' tumor), and yolk sac tumors." (PMID 31024850, 2019). "Immunostaining has revealed the co-expression of GPC3 and β-catenin in the tissues of hepatoblastoma." (PMID 31511432, 2019). "It is suggested that GPC3-induced activation of Wnt/β-catenin pathway is responsible for the development of hepatoblastoma." (PMID 31511432, 2019). "Accordingly, scientists have developed antibodies against GPC3 and explored their usefulness in hepatoblastoma." (PMID 31511432, 2019). "Although highly expressed, multiple studies have found that soluble GPC3 is an inferior serum biomarker of hepatoblastoma response compared with alpha fetoprotein, the current standard of care." (PMID 30873384, 2019). "Glypican 3 (GPC3), a heparan sulfate proteoglycan, is a cell surface oncofetal protein, which is highly expressed in number of pediatric tumors including hepatoblastomas." (PMID 31511432, 2019). "To exclude Wnt signaling, we chose HepG2, a GPC3-positive hepatoblastoma cell line expressing a constitutively activated β-catenin, to establish a xenograft model and evaluate the anti-tumor activity of the HS20 antibody." (PMID 26332121, 2015). "Western blot analysis showed the decreased expression of HB‐associated genes like AFP, OCT4, GPC3, and DUSP9 in IGF2 KD HepG2 cells, indicating that decreasing IGF2 could reduce hepatoblastoma stemness." (PMID 40271711, 2025).
hepatoblastoma (continued). "The Western blot analysis of IGF2‐treated cells demonstrated increased activation of the IGF2‐related signaling pathway and the increased expression of HB‐associated proteins, including AFP, OCT4, GPC3, DUSP9, and cMYC, indicating IGF2's role in sustaining hepatoblastoma stemness." (PMID 40271711, 2025). "RT‐PCR analysis showed the increased expression of HB‐associated genes like AFP, GPC3, and DUSP9, indicating that SREBF2 could enhance hepatoblastoma stemness." (PMID 40271711, 2025). "Western blot analysis showed that Fatostain treatment decreased the expression of HB‐associated genes like AFP, OCT4, GPC3, and DUSP9, indicating that SREBF2 inhibition could reduce hepatoblastoma stemness." (PMID 40271711, 2025). "Similarly, there are 20 shortest paths of length 3 between GPC3 and Hepatoblastoma including 6 diseases and 9 genes." (PMID 33587705, 2022). "Apart from inhibition of GPC3 expression, miR-4510 also decreased the transcriptional activity of Wnt/β-catenin pathway again suggesting the interactions between GPC3 and Wnt/β-catenin in inducing hepatoblastoma." (PMID 31511432, 2019). "In addition to affecting HCC cells, HS20 also blocks C-met activation in HepG2, a hepatoblastoma cell line with GPC3 expression." (PMID 26332121, 2015). "HUH6 and HepG2 cells exhibited stronger transcriptomic activation of AFP, DUSP9, GPC3, DLK1, MYC compared to other non‐hepatoblastoma cell lines." (PMID 40271711, 2025). "Due to the high heterogeneity of hepatoblastoma, the expression distribution of DUSP9 and GPC3 exhibited both homogeneity and heterogeneity." (PMID 40271711, 2025). "GPC3 modulates MAPK and Wnt/β-catenin signaling in hepatoblastoma, as observed in the HEPG2 cell line, highlighting it as a potential therapeutic target." (PMID 39684755, 2024). "Meanwhile, other known markers of hepatoblastoma, including AFP, DLK1, and GPC3, were upregulated in the epithelial (similarly in both fetal and embryonal) but not mesenchymal components." (PMID 39567523, 2024). "Western blot showed that GPC3 was highly expressed in HCC cell lines (Hep3B and Huh-7), as well as in HepG2, a hepatoblastoma cell line." (PMID 32746924, 2020). "Clusters 0, 2, and 4, characterized by high expression of known hepatoblastoma markers, including AFP, DLK1, and GPC3, were shared among all the tumoroids, while the remaining clusters of cells were more heterogeneously represented across the different tumoroids." (PMID 39567523, 2024). "We first performed a transcriptomic evaluation of the two well‐recognized hepatoblastoma cell lines, HepG2 and HUH6, using Pearson's analysis with gene signatures in the public GSE168997 dataset to elucidate IGF2′′s role in hepatoblastoma (AFP, DUSP9, GPC3, DLK1, MYC, EPCAM, KRT8, and LIN28B)." (PMID 40271711, 2025). "Additionally, we searched for malignant HB‐like cells in 28 hepatoblastoma tissues with prognostic information using DUSP9 and GPC3 immunohistochemical staining to further determine the correlation between malignant HB‐like cells and the prognosis of hepatoblastoma patients." (PMID 40271711, 2025). "There has been an exploration of new targets in the management of hepatoblastoma including signal transducer and activator of transcription signaling 3 (STAT3); NOTCH receptors and their ligands; PI3K/Akt, ERK and p38 signaling pathways; GPC3; PIM Kinases; ROCK1; mTOR and YAP." (PMID 31511432, 2019). "There are a variety of studies that demonstrate that GPC3 is nearly universally expressed on most hepatoblastomas although may be absent in less typical subtypes (e.g., teratoid) or portions of hepatoblastoma with mesenchymal differentiation." (PMID 30873384, 2019). "One potential diagnostic pitfall is that malignant rhabdoid tumors may express Glypican-3 and beta catenin, proteins that can also be expressed in hepatoblastomas, therefore these markers are not of use in helping to distinguish between these two different tumor types." (PMID 31835848, 2019).
breast carcinoma (38 papers, 2012 to 2025). "For example, expression of GPC5 showed to be suppressed in different kidney cancers and expression of GPC3 appeared to be downregulated in several thoracic associated cancers including breast cancer." (PMID 36944188, 2023). "We found that high levels of GPC3 expression are associated with a longer survival in breast cancer patients." (PMID 33742285, 2021). "We found that high GPC3 levels were associated with a better prognosis in overall breast cancer patients." (PMID 33742285, 2021). "Consequently, we propose the use of GPC3 as a diagnostic biomarker for identifying some of breast cancer-specific histological subtypes such as Paget’s disease and intraductal carcinomas." (PMID 36676710, 2022). "Moreover, GPC3 ectopic expression has led to increased susceptibility of breast cancer cells to apoptosis induced by increased serum depletion." (PMID 36676710, 2022). "Additionally, glypican-3 was associated with the inhibition of invasion and metastasis of a mammary carcinoma cell line in vivo." (PMID 25168166, 2014). "Materials and Methods: GPC3 expression was immunohistochemically evaluated in 230 breast cancer patients along with eight normal tissues and its associations to clinical and demographic characteristics, as well as immunohistochemical biomarkers for breast cancer." (PMID 36676710, 2022). "Glypican-3 (GPC3): A novel target being explored in early-phase clinical trials for its potential to be highly expressed on breast cancer cells while minimally present on normal tissues." (PMID 40940995, 2025). "P38 MAPK pathway: In breast cancer cells, GPC3 has been shown to reverse the EMT, prevent metastatic spread, and induce dormancy at secondary sites by activating the p38 mitogen-activated protein kinase (MAPK) pathway." (PMID 40422229, 2025). "GPC3 regulates autocrine and paracrine secretion in breast cancer cells by suppressing the canonical Wnt pathway." (PMID 38473810, 2024). "Glypican-3 (GPC3) is a proteoglycan that has a high level of expression in normal breast tissue but a lower level of expression in breast cancer." (PMID 39850890, 2024). "The results showed a highly significant correlation between GPC3 expression and the histological subtype of breast cancer (p = 0.001)." (PMID 36676710, 2022). "By using immunohistochemistry, we successfully characterised GPC3 protein expression in different breast cancer subtypes of Paget’s disease and intraductal and mucinous carcinomas." (PMID 36676710, 2022). "A similar pattern of expression was also demonstrated in other studies in certain subtypes of breast cancers, while other subtypes such as mucinous carcinoma showed a different mode of GPC3 expression." (PMID 36676710, 2022). "Such heterogeneity in GPC3 expression between different subtypes of breast cancers is obvious and has manifested clearly in all studies examining GPC3 expression in breast cancer." (PMID 36676710, 2022). "A proposed mechanism for this finding has been reported before, where downregulation of GPC3 expression was determined in breast cancers because of the GPC3 promoter hypermethylation." (PMID 36676710, 2022). "A possible explanation for these results came from two studies reporting the absence or weak expression of GPC3 in certain breast cancer subtypes due to the silencing of GPC3 by GPC3 promoter hypermethylation." (PMID 36676710, 2022). "In other words, some breast cancer subtypes show GPC3 expression, such as Paget’s disease and intraductal and mucinous carcinomas, whereas other subtypes show no expression at all, such as invasive ductal carcinomas." (PMID 36676710, 2022). "The current study demonstrated promising results where GPC3 expression significantly differentiated Paget’s disease and intraductal carcinomas from other breast cancer histological subtypes." (PMID 36676710, 2022). "This means that GPC3 was frequently expressed in patients with more favourable histological subtypes of breast cancer." (PMID 36676710, 2022).
breast carcinoma (continued). "GPC3 expression was determined in 7.5% (18 cases) of breast cancers, where the expression was localised at the cell nucleus or cytoplasm." (PMID 36676710, 2022). "Similar results were also obtained in another study demonstrating that breast cancer samples displayed relatively lower levels of GPC3 mRNA compared to normal tissue samples." (PMID 36676710, 2022). "This is a novel finding, as GPC3 expression was able to significantly differentiate Paget’s disease and intraductal carcinoma from other breast cancer histological subtypes." (PMID 36676710, 2022). "In another study, GPC3 re-expression in aggressive breast cancer cells returned mesenchymal-like breast cancer cells to an epithelial phenotype as shown by the suppression of Snail, ZEB1, vimentin, and increased expression of E-cadherin." (PMID 36358747, 2022). "Such a finding was evident in the heterogeneity of GPC3 expression among different and certain breast cancer histological subtypes." (PMID 36676710, 2022). "Upregulation of GPC3 was shown to decrease cell proliferation in almost all breast cancer cell lines examined." (PMID 36676710, 2022). "In breast cancer, GPC3 silencing in low metastatic MCF7 breast cancer cells stimulates an aggressive phenotype with EMT features; while, on the other hand, induction of its expression attenuates the aggressiveness of MDA-MB-231 cells, leading to MET." (PMID 36358747, 2022). "This heterogeneity in GPC3 expression was clearly manifested in our cohort study and across many studies, and is proposed as a characteristic event in specific subtypes of breast cancers." (PMID 36676710, 2022). "On this basis, the current study aims to gain a better insight into GPC3 overexpression in a wide range of different subtypes of breast cancer and to correlate it with the expression of hormone receptors and other related molecules." (PMID 36676710, 2022). "Recent evidence shows that GPC3 expression has been found in lower levels in breast cancer tissues compared to healthy normal tissues, although the studies were carried out in small sample sizes and focused on limited subtypes of breast cancer." (PMID 36676710, 2022). "Overall, these results encourage further research investigating GPC3 expression and its relation to hormone receptors in certain breast cancer subtypes." (PMID 36676710, 2022). "This is a strong indication for the idea to conduct research on the possible induction of expression of GPC3 in breast cancer patients with the triple-negative subtype, as possibly metastasis of the breast cancer cells can be reduced." (PMID 33742285, 2021). "As a step in the nearer future in line with our findings we propose GPC3 as a marker to identify the prognosis of breast cancer patients." (PMID 33742285, 2021). "Our survival analysis has shown that high gene expression levels of GPC3 significantly lead to a longer RFS in breast cancer patients overall." (PMID 33742285, 2021). "Further research into the potency of GPC3 as an anticancer therapeutic would definitely be a valuable step in the battle to fight breast cancer." (PMID 33742285, 2021). "Overexpression of GPC3 reduces progression and metastasis of breast cancer cells LM3 through targeting canonical Wnt pathway." (PMID 33302876, 2020). "GPC3 silencing promoted breast cancer growth, while ectopic re-expression of GPC3 inhibited growth in vitro." (PMID 33330449, 2020). "The up-regulation of GPC3 significantly inhibited the proliferation and metastasis of breast cancer cells, illustrating that GPC3 functions as a tumour suppressive gene in breast cancer." (PMID 31160489, 2019). "In view of the clinical and translational usefulness of GPC3, in the current study we generated and characterized engineered human breast cancer cells to evaluate the role of GPC3 on human mammary tumor progression." (PMID 27507057, 2016).
breast carcinoma (continued). "We also showed that GPC3 expression decreased the clonogenic efficiency of breast cancer cells, since GPC3 silenced MCF-7 cells showed higher aptitude to grow at low density while GPC3 overexpressing MDA-MB231 cells were less clonogenic than their controls." (PMID 27507057, 2016). "On the other side, GPC3 overexpression induced the mesenchymal-epithelial transition (MET) of MDA-MB231 breast cancer cells, which re-expressed E-Cadherin and reduced the expression of vimentin and N-Cadherin." (PMID 27507057, 2016). "In summary, our results show that GPC3 would act as an inductor of cell death in stressed breast cancer cells." (PMID 27507057, 2016). "All together, our results suggest that GPC3 is able to modulate different growth properties of breast cancer cells." (PMID 27507057, 2016). "Regarding breast cancer, we have recently performed comparative studies of GPC3 expression, indicating lower GPC3 levels in tumors as compared to peritumor tissues." (PMID 27507057, 2016). "This is, to our knowledge, the first report indicating that GPC3 is able to modulate anchorage-independent 3D growth in breast cancer cells." (PMID 27507057, 2016). "Overall, these data indicate that GPC3 suppressed low density growth as well as activated cell-cell adhesion and spheroids formation of the mammary cancer cells." (PMID 27507057, 2016). "We showed that when human mammary tumor cells express GPC3, the canonical Wnt pathway is inhibited, the transcription factors ZEB1 is downregulated and the key marker of epithelial phenotype E-Cadherin is upregulated." (PMID 27507057, 2016). "All together, our in vitro and in vivo results show that GPC3 is able to promote MET in mammary tumor cells, inducing phenotypic changes and regulating growth, death, migration and invasive/metastatic ability." (PMID 27507057, 2016). "The expression of GPC3 is silenced in human breast cancer, but ectopic expression of GPC3 revealed that this molecule can act as a negative regulator of breast cancer cell growth." (PMID 25140302, 2014). "Intriguingly, the GPC3 gene silencing has been identified in human breast cancer cells, through a mechanism which involves the hypermethylation of the GPC3 promoter." (PMID 25140302, 2014). "Most of the studies concerning the roles of GPCs in breast cancer progression focus on the role of the GPC3 member." (PMID 25140302, 2014). "Consequently, it has been deduced to potentially serve as a selective target for the development of novel therapeutics for subtypes of breast cancer expressing GPC3." (PMID 39188449, 2024). "The studies, however, have yielded contradictory results about GPC3 expression in breast cancer." (PMID 36676710, 2022). "Therefore, the current study aims to analyse GPC3 expression across a large panel of different breast cancer subtypes." (PMID 36676710, 2022). "Moreover, a public database consisting of breast cancer patients’ survival data and GPC3 gene expression information was used to assess the prognostic value of GPC3 in the survival of breast cancer patients." (PMID 36676710, 2022). "The positive impact on survival is consistent with the findings of several other studies, which have shown that GPC3 may have a unique protective function in the development of human breast cancer." (PMID 36676710, 2022). "Limited studies have investigated GPC3 expression and its role in breast cancer progression." (PMID 36676710, 2022). "This indicates that GPC3 may be preferentially expressed in patients with more favourable histological subtypes of breast cancer." (PMID 36676710, 2022). "Furthermore, in a murine model, GPC3 expression was shown to suppress metastasis of breast cancer cells by reducing cell proliferation, survival, and motility." (PMID 36676710, 2022). "Importantly, GPC3 mRNA expression was revealed as a strong prognostic predictor of breast cancer patients." (PMID 36676710, 2022). "Currently, there is much debate regarding GPC3 expression in breast cancers." (PMID 36676710, 2022).